APP (amyloid beta precursor protein)
Diseases named in the same sentence as APP in open-access papers (continued):
Sharing a sentence is not in itself a finding about the gene and the disease.
Alzheimer disease (continued). "In a mouse model of APP/PS1 mice, besides inhibiting NLRP3-dependent symptoms seen in Alzheimer’s disease, MCC950 also increased the uptake of β-amyloid plaques and ameliorated neurological outcomes by inducing their clearance." (PMID 31892810, 2019). "Previous studies have demonstrated that Sp1 overexpression upregulates APP and BACE1 expression, which is involved in Alzheimer's disease." (PMID 31049134, 2019). "The effects of uncouplers on protein secretion seem to be complex, as illustrated here for the beta-amyloid precursor protein (APP), a protein playing a key role in the etiology of Alzheimer’s disease." (PMID 31366145, 2019). "Since we also present evidence that KLC1 serine-460 phosphorylation affects axonal transport and processing of APP, our results suggest that increased KLC1 serine-460 phosphorylation contributes to the pathogenesis of Alzheimer’s disease." (PMID 31806024, 2019). "On the other hand, CBD induced ubiquitination of the amyloid precursor protein (APP), an indicator of cellular changes in the brain of people with Alzheimer’s disease, when evaluated in human neuroblastoma cells (SHSY5YAPP+)." (PMID 31881765, 2019). "Over the past 25 years, APP has been the object of intense interest because proteolytic cleavage in the juxtamembrane and transmembrane domains generates the beta-amyloid peptide that accumulates in patients with Alzheimer disease (AD)." (PMID 31318883, 2019). "Microvesicles in the CSF of 15 patients with Alzheimer’s disease and 15 controls were analyzed by flow cytometry regarding the levels of CD3, CD4, CD45, CD64, BACE1, Aβ, APP and tau." (PMID 31068645, 2019). "In the KEGG disease database, APP and PSEN1 are identified as representative genes for Alzheimer's disease." (PMID 31017923, 2019). "In APP/PS1/Ear2(−/−) mice, a transgenic model of Alzheimer’s disease, MRI detected a reduced MRI signal in LC." (PMID 30903359, 2019). "Recently, genus Odoribacter was reported to be significantly higher in APP/PS1 mice, a rodent model of Alzheimer’s disease, compared with wild type mice; this result is consistent with our findings that elevated Odoribacter is associated with CD." (PMID 31123221, 2019). "Overall, the brain histopathology and behavioral assessment showed that the APP+PS1 rats demonstrated behavioral characteristics and vascular changes similar to those commonly observed in patients with Alzheimer’s disease." (PMID 29641600, 2018). "Indeed, synaptotagmins seem to play a role as APP interactors in promoting Aβ generation: the application of the present methodology to assess their level could help to better clarify their possible involvement in Alzheimer’s disease etiopathogenesis." (PMID 29670520, 2018). "In the present study we investigated persistent DSBs, and markers of two repair pathways - non-homologous end joining (NHEJ) and homologous recombination-directed repair (HR) - in APP/PSEN1 mice, a model of Alzheimer’s disease-related amyloidosis." (PMID 29618789, 2018). "We show here that miR-19b-3p targets MID1, a protein that we have previously shown to induce protein expression of two mRNAs that are crucial for the development of amyloid plaques in Alzheimer’s disease, namely BACE1 and APP." (PMID 29293623, 2018). "Platelets express amyloid-precursor protein (APP), release beta-amyloid (Aβ) and are stimulated (pre-activated) in Alzheimer’s disease (AD)." (PMID 30341392, 2018). "Concerning the APP/PS1 mice, the BBB is known to be affected in neurodegenerative disorders like Alzheimer’s disease." (PMID 28420415, 2017). "Methysticin improves cognition and ameliorates gliosis in APP/PS1 mice, and carnosic acid is protective in multiple Alzheimer’s disease mouse models." (PMID 28820437, 2017). "β-amyloid (Aβ), a cleavage product of amyloid precursor protein (APP), is the major component of extracellular plaques found in the brain tissue of patients with Alzheimer’s disease." (PMID 28737703, 2017).
Alzheimer disease (continued). "The amyloid precursor protein (APP) harbors physiological roles at synapses and is central to Alzheimer’s disease (AD) pathogenesis." (PMID 28682239, 2017). "Human genetic evidence indicates that the amyloid precursor protein (APP) plays an important physiological role in the central nervous system and is central to the pathogenesis of Alzheimer’s disease (AD)." (PMID 28682239, 2017). "The production of Aβ from amyloid precursor protein (APP) is the most well-studied component of AD development, especially in early-onset Alzheimer's disease (EOAD)." (PMID 29311768, 2017). "The biological function of the amyloid precursor protein (APP) as a signaling molecule in the brain remains unresolved, presenting a significant hurdle to understand its role in late-onset Alzheimer’s disease (AD) etiology." (PMID 29066835, 2017). "Emerging evidence suggests that alpha-processing single transmembrane proteins, amyloid precursor protein (APP) and anti-aging protein Klotho, are likely to be involved in the progression of Alzheimer’s disease (AD)." (PMID 29163135, 2017). "Amyloid-β, the misfolded protein cleaved from amyloid precursor protein (APP), is the key constituent of amyloid plaques seen in Alzheimer’s disease (AD) and is thought to contribute to the observed toxicity and cell death along with tau." (PMID 29326640, 2017). "δ-secretase, also known as asparagine endopeptidase (AEP) or legumain, is a lysosomal cysteine protease that cleaves both amyloid precursor protein (APP) and tau, mediating the amyloid-β and tau pathology in Alzheimer's disease (AD)." (PMID 28345579, 2017). "For example, abnormal N-glycosylation of neurotransmitter-related proteins and amyloid precursor protein (APP) has been reported in patients with schizophrenia and Alzheimer disease (AD)." (PMID 28746350, 2017). "In this study, we examined the effects of ABCG1 and ABCG4 on amyloid precursor protein (APP) processing, the product of which, amyloid β (Aβ), is involved in the pathogenesis of Alzheimer’s disease." (PMID 27196068, 2016). "More than 20 years ago, the amyloid precursor protein (APP) was identified as the precursor protein of the Aβ peptide, the main component of senile plaques in brains affected by Alzheimer’s disease." (PMID 27092780, 2016). "A growing body of evidence suggests that soluble alpha-amyloid precursor protein (sAPPalpha), a cleavage product of APP, has neurotrophic and neuroprotective properties in Alzheimer disease." (PMID 26973652, 2016). "Processing of APP by BACE1 is the rate-limiting step in the production of Aβ, and therefore, BACE1 is a major therapeutic target for the treatment of Alzheimer’s disease." (PMID 27456313, 2016). "It was further demonstrated that familial Alzheimer’s disease (FAD) mutant APP (V717F) transgenic mouse and FAD-APP transfected cultured human cells, both produced chromosome missegregation and aneuploidy in both brains and peripheral cells." (PMID 26751496, 2016). "In the nervous system, the expression of CLU (clusterin) is elevated in neuropathological conditions, such as Alzheimer’s disease, where CLU co-precipitates with APP, suggesting a physiological interaction." (PMID 27748412, 2016). "If this is the case, studies using neurons are essential to understand the effects of ABCG1 on APP processing and Aβ secretion in the CNS and to reveal the relationship between the expression of ABCG1 and Alzheimer’s disease." (PMID 27196068, 2016). "Amyloid precursor protein (APP) is well known for its function in the pathogenesis of neurodegenerative disorders, such as Alzheimer’s disease (AD)." (PMID 28008944, 2016). "The story began in the early 1980s with research into the genetics of Amyloid Precursor Protein (APP) and its linkage to early-onset Alzheimer's disease." (PMID 26594384, 2015). "However, as the cellular function of APP remained unclear, describing how loss of APP function could contribute to Alzheimer’s disease was not possible to date." (PMID 26125944, 2015).
Alzheimer disease (continued). "There is convincing evidence from the literature on Alzheimer's disease that KLK6, the most abundant kallikrein-related peptidase in the central nervous system, cleaves the amyloid precursor protein (APP), a transmembrane glycoprotein from which Aβ derives." (PMID 26783378, 2015). "Proteolytic processing of amyloid-β precursor protein (APP) by beta-site APP cleaving enzyme 1 (BACE1) is the initial step in the production of amyloid beta (Aβ), which accumulates in senile plaques in Alzheimer’s disease (AD)." (PMID 26053850, 2015). "In the present study, we show that IDN5706 disrupts APP glycosylation, and stimulates the degradation of iAPP through Atg5-dependent autophagy, with a resulting reduction in the processing of APP to CTFs, which could have beneficial effects to Alzheimer's disease." (PMID 26308941, 2015). "We show here that this novel property of DHA is also significant in the hippocampus of wild-type mice and, to a lesser extent in APP/PS1 transgenic mice, a familial model of Alzheimer's disease." (PMID 26257655, 2015). "For this study, we examined the process used in creating a 3D model representation of the overall structure of amyloid precursor protein (APP), a molecule which is considered important in the development of Alzheimer's Disease." (PMID 26329268, 2015). "The role of P2X7 receptor has been more intensively studied in Alzheimer's disease, where the effects of the signalling cascades coupled to P2X7 activation on APP processing have been reported." (PMID 25848496, 2015). "In this particular case, it is a protein interaction network centered on amyloid-beta precursor protein (APP), by common consensus one of the key players in the pathogenesis of Alzheimer's disease." (PMID 26041885, 2015). "Proteins central to neurodegenerative diseases, such as Htt in HD, as well as amyloid precursor protein (APP), tau, and presenilin in Alzheimer’s disease (AD) are all caspase-6 substrates." (PMID 26505998, 2015). "In regard to Alzheimer's disease, HDAC inhibitors exhibit various beneficial effects in mouse models of AD, such as APP/PS1 mouse models of familial AD, and the CK-p25 mouse model of AD-related neurodegeneration and memory decline." (PMID 26041885, 2015). "γ-secretase is a transmembrane protease responsible for the eventual cleavage of amyloid precursor protein (APP) to generate Aβ, thus it is considered a principal therapeutic target in Alzheimer's disease." (PMID 25136630, 2014). "γ-Secretase is a four subunit, 19-pass transmembrane enzyme that cleaves amyloid precursor protein (APP), catalyzing the formation of amyloid beta (Aβ) peptides that form amyloid plaques, which contribute to Alzheimer’s disease (AD) pathogenesis." (PMID 25610395, 2014). "When orally administered before and after the onset of Alzheimer's disease symptoms, KMS88009 significantly reduced assembly of amyloid-β oligomers and improved cognitive behaviors in the APP/PS1 double transgenic mouse model." (PMID 24760018, 2014). "APP/Presenilin-1 (PS1) mice, which develop symptoms similar to Alzheimer's disease, were crossed with NLRP3−/− or Casp-1−/− mice." (PMID 24834051, 2014). "Comparison of APP/PS1 and age-matched WT control mice revealed a stronger expression of EPOR but a weaker one of EPO in the Alzheimer’s disease (AD) model mice." (PMID 24124607, 2013). "The amyloid precursor protein (APP) for instance fulfills distinct functions when cleaved by different proteases, at worst leading to neurodegeneration and the development of Alzheimer's disease." (PMID 23757215, 2013). "Amyloid precursor protein (APP) contributes to the production of beta-amyloid (Aβ), which is a major component of senile plaques in the brain of Alzheimer’s disease (AD) patients." (PMID 23704887, 2013).
Alzheimer disease (continued). "MiR-34c (but not miR-34a and miR-34b) is highly enriched in hippocampal regions and its expression is further upregulated by aging (24 months old mice), in mice models of amyloidosis (12 months APP/PS1-21 mice) and in Alzheimer's disease patients." (PMID 23339066, 2013). "The amyloid precursor protein (APP) and its processing by the α-, β- and γ-secretases is widely believed to play a central role during the development of Alzheimer ́s disease." (PMID 24324731, 2013). "Previous studies have shown that Rab6 impairs the processing of the amyloid precursor protein (APP), which is cleaved to β-amyloid in brains of patients suffering from Alzheimer’s Disease." (PMID 23737971, 2013). "AD, Alzheimer’s Disease; Aβ, amyloid beta; APP, amyloid precursor protein; GFAP, glial fibrillary acidic protein; Iba1, ionized calcium binding adaptor molecule 1; PSD95, postsynaptic density protein 95; TNFα, tumor necrosis factor α." (PMID 22673542, 2012). "One such example is an unexpected activity of the amyloid precursor protein (APP), for which involvement in Alzheimer's disease has been established, in radial migration by controlling Disabled-1 (Dab1) activity downstream." (PMID 22428039, 2012). "In the context of Alzheimer’s disease, BACE1 and BACE2 cleavage of APP has been well characterized, and both conserved and unique cleavage sites on APP have been demonstrated for the two BACE proteins." (PMID 22797723, 2012). "Homodimerization of Amyloid Precursor Protein (APP), a key mechanism in the etiology of Alzheimer’s disease, was measured on this original set-up." (PMID 22973448, 2012). "Here we applied tr-FAIM to the homodimerization of Amyloid Precursor Protein (APP), a key player in Alzheimer’s disease (AD)." (PMID 22973448, 2012). "Amyloid β (Aβ) peptides are proteolytic products from amyloid precursor protein (APP) and are thought to play a role in Alzheimer disease (AD) pathogenesis." (PMID 22194817, 2011). "The amyloid precursor protein (APP) is well known for giving rise to the amyloid-β peptide and for its role in Alzheimer's disease." (PMID 21829538, 2011). "The enzyme involved in the production of β-amyloid peptide (Aβ) of Alzheimer's disease, BACE1, functions optimally at lower pH, which led us to investigate a potential role of lactic acid in the processing of amyloid precursor protein (APP)." (PMID 21072203, 2010). "Cleavage of the amyloid precursor protein (APP) by β- and γ-secretase gives rise to the amyloid β-protein (Aβ) found in senile plaques (SP) in Alzheimer's disease (AD)." (PMID 20849576, 2010). "The in vitro and in vivo selectivity of ELN475516 demonstrates that discovery of APP selective GSI's is feasible, and that APP selective GSI's offer potentially safer candidates as therapeutics for Alzheimer's disease." (PMID 21190552, 2010). "For example, in Down syndrome, duplication of the 21st chromosome, which contains the amyloid beta precursor protein (APP) gene, leads to accumulation of amyloid beta and Alzheimer's disease pathology." (PMID 21124796, 2010). "The metabolism of the amyloid precursor protein (APP) and tau are central to the pathobiology of Alzheimer's disease (AD)." (PMID 19771166, 2009). "For its role in APP processing and Aβ generation, BACE1 is a central actor in the pathogenesis of Alzheimer's disease, and β-secretase inhibition has become a therapeutic goal." (PMID 20041192, 2009). "To determine whether TUDCA exerts protective effects on cognitive decline in Alzheimer’s disease, we administered TUDCA to APP/PS1 mice beginning at 6 months of age, when early pathological features start to emerge." (PMID 41614917, 2026).
Alzheimer disease (continued). "This is consistent with previous findings showing that increased Tau levels in a mouse model of Alzheimer’s disease do not alter APP steady-state levels or affect Aβ pathology." (PMID 41516328, 2026). "Moreover, early subcutaneous injection of GA in APP/PS1 mice, a model of Alzheimer’s disease (AD), delayed disease progression, reduced amyloid beta plaque burden, regulated neuroinflammation, promoted neuroprotection, and induced dendritic-like microglia." (PMID 41301925, 2025). "In humans, a circRNA derived from the amyloid β precursor protein (APP) gene, known as circAβ-a, can be translated into a novel Aβ-containing polypeptide in the brains of both Alzheimer’s disease patients and non-dementia individuals." (PMID 39966624, 2025). "The attenuation in cortical θ–low-γ PAC in APP/PS1 mice is evident already at 3 months and may reflect a pathophysiological change of relevance to understanding E/I changes in Alzheimer's disease." (PMID 41293234, 2025). "The interactions can be essential both for the choice of secretase cleavage-processing pathways crucial for Alzheimer’s disease pathogenesis and for the ostensibly multifaceted (and not yet fully explored) normal function of APP." (PMID 39859269, 2025). "Furthermore, it was revealed that circRNA Cwc27 was upregulated in neurons and brains of APP/PS1 mice, as well as in temporal cortex and blood of Alzheimer’s disease patients." (PMID 41245147, 2025). "APP/PS1 and other double or triple transgenic mice are commonly used to recapitulate amyloid plaque deposition and neurofibrillary tangle formation seen in Alzheimer’s disease." (PMID 40725274, 2025). "In 2009, no pathogenic variants were identified in the APP, PSEN1, and PSEN2 genes in the three living patients with Alzheimer's disease, and these negative findings were also confirmed in ES." (PMID 39810256, 2025). "FA-induced decreased expression levels of BACE1 and APP and increased expression of MMP2 and MMP9 were found by cellular experiments, and FA may be a potential herbal component for the treatment of Alzheimer’s disease." (PMID 39372201, 2024). "The first successful mouse model of Alzheimer’s disease was reported in 1995 with the generation of the PDAPP mice, which were obtained by the overexpression of gene coding for the amyloid precursor protein (APP)." (PMID 39595581, 2024). "In addition, gelsolin was found to reduce amyloid-ß levels in APP/PS1 transgenic mice, suggesting that it plays a protective role in Alzheimer’s disease." (PMID 39125436, 2024). "In an Alzheimer’s disease model, we demonstrate silencing of mutant APPswe mRNA without altering the wild-type APP mRNA." (PMID 38972974, 2024). "Barros-Viegas A.T., Carmona V., Ferreiro E., Guedes J., Cardoso A.M.,Cunha P., de Almeida L.P., de Oliveira C.R., de Magalhães J.P.,Peça J., Cardoso A.L. miRNA-31 improves cognition and abolishesamyloid-β pathology by targeting APP and BACE1 in an animalmodel of Alzheimer’s disease." (PMID 38680184, 2024). "For instance, in mouse models of Alzheimer's disease, overexpression of sFKN using rAAV in Tg4510 mice (but not in APP/PS1 mice) led to reduced tau phosphorylation and deposition, decreased neuronal loss and brain atrophy, and cognitive improvements." (PMID 38311721, 2024). "Furthermore, it has been demonstrated that fecal transplantation from aged APP/PS1 transgenic mice into young mice resulted in a significant decline in cognitive function and showed prominent Alzheimer’s disease pathological characteristics." (PMID 39203778, 2024). "Additionally, we established a Zn-rich mouse model using two months old APP/PS1 mice, which is a transgenic mouse model for Alzheimer’s disease (AD)." (PMID 39689159, 2024). "Moreover, it has demonstrated the ability to improve memory deficits in APP/PS1 transgenic mice, a widely used model for Alzheimer’s disease." (PMID 39684612, 2024).